BRCA2 (BRCA2 DNA repair associated)
Diseases named in the same sentence as BRCA2 in open-access papers (continued):
Sharing a sentence is not in itself a finding about the gene and the disease.
cancer (continued). "Precise estimates could inform cancer surveillance and risk-reduction options for survivors of BC carrying BRCA1/BRCA2 PVs." (PMID 39475295, 2025). "In addition to splice variants, it is likely that modifier genes and genetic background, which have been shown to modulate and prolong embryonic survival in Brca2-null mice, as well as possibly chance events, contribute to the emerging cancer phenotype." (PMID 40724944, 2025). "BRCA2 mutant cancer is currently treated with platinum and PARP inhibitors." (PMID 41162355, 2025). "In the largest pan-cancer analysis of BRCA1/2 alterations published to date (including 7186 prostate cancers), it was shown that germline mutations were present in 35% of patients with BRCA1-altered mCRPC compared with 50% of patients with BRCA2 altered mCRPC." (PMID 39333696, 2025). "The PGV rate was largely contributed to by BRCA2 (1.7%), ATM (1.3%), CHEK2 (1.1%) and BRCA1 (0.5%) and PGVs in these genes were found at significantly higher rates in the high risk localized and advanced PCa cohort compared to cancer-free males." (PMID 40832411, 2025). "We next investigated whether the combination of CldU and PARPi exerts a synergistic effect in BRCA2-mutant cancer cells." (PMID 41347092, 2025). "Notably, BRCA1, BRCA2, and AURKA played significant regulatory roles within the gene expression network and are strongly implicated in cancer onset and progression." (PMID 40666234, 2025). "This may partly be attributed to shared genetic predispositions, including mutations in genes like BRCA1, BRCA2, MLH1 and MLH2, which are associated with susceptibility to both cancers." (PMID 40444502, 2025). "The BRCA2 gene is essential for preserving DNA integrity and preventing the development of cancer." (PMID 40141415, 2025). "Therefore, it is understood that the genes BRCA1, BRCA2, and PALB2 are key cancer susceptibility genes." (PMID 40869938, 2025). "By analogy, BRCAness cancers, i.e., those that share molecular features of germline BRCA1 or BRCA2 mutated cancers (gBRCAm), also phenocopy the platinum-salt or poly(adenosine diphosphate–ribose) polymerase (PARP) inhibitor sensitivity seen in gBRCAm cancers." (PMID 40138429, 2025). "Genetic studies in Latin America have expanded, but further efforts are needed to understand cancer susceptibility genes beyond BRCA1 and BRCA2, especially by characterizing the prevalence and spectrum of pathogenic or likely pathogenic variants (PVs) in the region." (PMID 40065011, 2025). "Interestingly, WRN and BRCA2 co-regulate replication fork stabilization in cancer cells and promote cell proliferation." (PMID 40649870, 2025). "In this study, we assessed the sensitivity to CldU across eight BRCA2-mutant cancer cell lines." (PMID 41347092, 2025). "Previously, reversal mutation of BRCA2, loss of PARP1 protein expression, and overexpression of drug efflux pumps ABCB1 (p‐glycoprotein) and ABCG2 (BCRP) have been linked to acquired resistance to PAPRi in BRCA2 mutant cancer." (PMID 40874518, 2025).
cancer (continued). "Although studies on the impact of environmental and lifestyle variables on cancer are ongoing, there is little proof to support that they might produce BRCA1 or BRCA2 mutations on their own." (PMID 40141415, 2025). "An HRD score of at least 42 was found in only a half of BRCA2-positive carcinomas." (PMID 41465280, 2025). "BRCA1 and BRCA2 gene mutations account for most actionable genetic BC predispositions and are increasingly used for personalized BC management and PARP inhibitors therapy of BRCA-related cancer." (PMID 38725624, 2024). "Additionally, CRISPR-based gene editing can be used to repair genetic mutations that cause cancer, such as in the case of inherited forms of cancer caused by BRCA1 and BRCA2 mutations." (PMID 38195537, 2024). "All 352 male probands with HBOC syndrome-associated tumours, after appropriate genetic counselling, aimed at ascertaining the criteria concerning personal and family history of cancer recommended by the AIOM national guidelines, were genetically tested for germline variants in BRCA1 and BRCA2 genes." (PMID 38974244, 2024). "We propose that modulating the dynamicity of telomeric G4 and targeting TERRA-R-loops in telomeric LLPS maintenance may represent effective therapeutic strategies for treating ALT-like cancers with APBs, including those with BRCA2 disruptions." (PMID 38587189, 2024). "cfDNA sequencing using MSK-ACCESS, an ultra-high coverage NGS panel that includes exons from 129 cancer-associated genes, including all exons of BRCA2, did not detect any resistance mechanism compared to baseline cfDNA30." (PMID 38355834, 2024). "Likewise, in almost all men affected by PC (87/95, 92%) no BRCA-associated genetic predisposition was found, except in 5 (5%) patients with family history of cancer who harboured germline PVs only in BRCA2 gene." (PMID 38974244, 2024). "The risks of other cancers are also elevated in BRCA1-, BRCA2-, and ATM-variant carriers." (PMID 38929805, 2024). "In the same cancer clone as NF2, we identified a BRCA2 (p.E51K) mutation was present in all tumors, which may represent a potential driver event, though evidence supporting this is currently limited." (PMID 39935847, 2024). "ATM, BRCA2, and BRCA1 mutations have been well characterized in breast, ovarian, and other cancers." (PMID 39132489, 2024). "HR deficiencies may be targeted through their sensitivity to acetaldehyde toxicity, as it has been shown in H1299 NSCLC carcinoma cell line depleted for BRCA2, and in other cancer cell lines from other types of cancers." (PMID 39682179, 2024). "Germline genetic testing for hereditary breast and ovarian cancer (HBOC) enables targeted treatment and risk management interventions for women who carry pathogenic or likely pathogenic (P/LP) variants in a cancer predisposition gene, such as BRCA1, BRCA2 or PALB2." (PMID 39766065, 2024). "Women may be at high risk due to a family history of cancer or a pathogenic or likely pathogenic variant in a cancer-susceptibility gene (such as BRCA1, BRCA2, or PALB2)." (PMID 38611036, 2024).
cancer (continued). "Despite our increasingly precise knowledge of how BRCA2 works at the molecular level, we still do not fully understand how patients carrying BRCA2 mutations develop cancer." (PMID 39711301, 2024). "PVs in BRCA1, BRCA2, CHEK2, and ATM have been linked to a wide variety of cancers." (PMID 38929805, 2024). "Our data provide a mechanistic basis for how BRCA2 shields against genomic instability by preventing HO-TRCs through both direct and indirect means occurring at predetermined genomic sites based on the pre-cancer transcriptome." (PMID 38830843, 2024). "DH PSV in either the BRCA1 or BRCA2 genes with other cancer susceptibility genes or two non-BRCA cancer susceptibility genes have been reported less frequently, especially in populations not exhibiting founder PSVs." (PMID 39102164, 2024). "In our previous article, using data from the Hospital-based Epidemiological Research Program at Aichi Cancer Center (HERPACC), we assessed the impact of Germline Pathogenic Variants (GPVs) of cancer-predisposing genes, such as BRCA1 or BRCA2, on breast cancer risk." (PMID 38403691, 2024). "However, interestingly, in the same cancer clone as NF2, we identified a potential BRCA2 driver mutation (p.E51K) present in all tumors along with a SETD2 (p.S1885N) mutation present only in the recurrence." (PMID 39935847, 2024). "Polymorphisms with intact NLS1, BRCA2 K3326* and BRCA2 E3342*, not cancer-associated (BS2) and properly localized (BS3), are outside Reactome’s scope." (PMID 38713862, 2024). "Additionally, we assessed BRCA1 and BRCA2 expression in normal esophageal cells and EC cells and found that HMGA1, BRCA1, and BRCA2 were highly expressed in cancer cells." (PMID 39690136, 2024). "The role of BRCA1 and BRCA2 proteins in the repair of DNA damage pathway raised the hypothesis that gBRCA carries have an increased sensitivity for chemotherapy, including both cancer as well as rapidly dividing cells such as bone marrow cells." (PMID 38345692, 2024). "Background/Objectives: BRCA1, BRCA2, ATM, and CHEK2 are known cancer predisposition genes (CPGs), but tumor risk in patients with simultaneous pathogenic variants (PVs) in CPGs remains largely unknown." (PMID 38929805, 2024). "Common mutations in DDR-associated genes, such as BRCA2 and ATM, in CDX2-suppressed cancers may offer additional therapeutic opportunities for treatment with PARP inhibitors or inhibitors of ATM that are in development." (PMID 39452477, 2024). "Nevertheless, this amount of BRCA2 protein seems to be sufficient for cancer-preventing functions." (PMID 39711301, 2024). "Investigating the interplay and molecular mechanism between BRCA1/BRCA2 and autophagy could provide further insights into cancer biology and therapeutic strategies promoting precision medicine." (PMID 39199310, 2024). "Notably, patients harboring VUS demonstrated elevated cancer worry scores across the study phases in contrast to those with BRCA1 and BRCA2 pathogenic variants or wild-type counterparts." (PMID 38500651, 2024). "Further understanding of these mechanisms may eventually pave the way for improved personalized cancer therapy of PALB2 mutation carriers, and possibly also to carriers of functionally related cancer susceptibility gene defects in e.g., BRCA1 and BRCA2." (PMID 38597967, 2024). "Notably, the SKP2 and its substrate BRCA2 emerged as a critical regulatory axis with implications for cancer progression and metastasis." (PMID 39062881, 2024). "Women with prevalent BC and carriers of BRCA1 and BRCA2 mutations did not have on-time annual screenings any more than women low cancer risk." (PMID 38564263, 2024). "Amplifying this point, 5 out of 6 BRCA2 carriers identified by this unselected approach did not meet any guideline and there is ample evidence of reduction in cancer-specific and all-cause mortality by standard of care gene-specific clinical management." (PMID 37861889, 2024).
cancer (continued). "Collectively, our results provide a mechanistic basis for how BRCA2 shields against genomic instability by preventing HO-TRCs through both direct and indirect means occurring at predetermined genomic sites based on the pre-cancer transcriptome." (PMID 38830843, 2024). "This fork recovery pathway depends on ubiquitination of PCNA at lysine 164 and is specifically activated in BRCA1- but not BRCA2-deficient cancer cells." (PMID 38943334, 2024). "“When you have cancer, you want to do all you can about it.” - Age 58, BRCA2." (PMID 38698439, 2024). "BOADICEA may be used to aid personalised cancer risk management and decision-making for BRCA1 and BRCA2 PV carriers." (PMID 38834293, 2024). "For example, patients with hereditary BRCA1/BRCA2 mutations can be diagnosed with cancer approximately 2 years earlier than patients without such mutations." (PMID 38279352, 2024). "As expected, genes including 53BP1 and PAXIP1 previously identified in murine models as synthetically viable in BRCA1/BRCA2-deficient tumors were not frequently altered in human cancers." (PMID 39198848, 2024). "BRCA2 mutations in women can cause familial, early-onset breast cancer, so understanding these mutations and their potential impact on the interaction with RPA will become vital in understanding DNA repair, specifically in cancer cells." (PMID 38397158, 2024). "However, the patient’s cancer subsequently acquired resistance with rising PSA and subsequent biopsy of a metastatic lymph node showed outgrowth of the clone with BRCA2 loss." (PMID 39623053, 2024). "This allows for us to formulate a hypothesis that in LSCC, SKP2 induces BRCA2 degradation through excessive ubiquitination, leading to further proliferation of tumor cells and facilitating cancer metastasis." (PMID 39062881, 2024). "Cells devoid of functional BRCA1 or BRCA2 proteins may undergo uncontrolled proliferation, leading to the development of cancer." (PMID 38809921, 2024). "From a cancer perspective, the most informative of these is a challenge provided and assessed by members of the ENIGMA consortium, using a total of 321 germline BRCA1/BRCA2 missense and in-frame indel variants." (PMID 38389099, 2024). "PARP inhibitors that target PARP1/2, such as olaparib and talazoparib, have been approved as anticancer agents for patients with breast and ovarian cancers bearing mutations in the homologous recombination (HR) factors BRCA1 and BRCA2, as well as for platinum-sensitive cancers." (PMID 38625917, 2024). "Several studies have investigated whether an enrichment for mutations affecting other genes would be detected in BRCA1 or BRCA2 cancers and provide a basis for the synthetic viable interactions." (PMID 39198848, 2024). "The corresponding cumulative BC risks for Singapore residents from the same birth cohort, where the underlying population cancer incidences are higher compared to Malaysia, were higher, varying by ancestry group between 57 and 61% for BRCA1, and between 43 and 47% for BRCA2 carriers." (PMID 38333895, 2024). "Additionally, we assessed the allele frequencies of the genes in the gnomAD non-cancer cohort (n = 134 187), which showed significant differences in BRCA1, BRCA2, CHEK2, MUTYH, MSH6, POLE, and ERCC3 genes in comparison to our non-HBOC groups." (PMID 39148954, 2024). "In addition to the interactions with BRCA1 and BRCA2, we also looked at the interactions between the KIF family proteins and other ACMG cancer-associated genes." (PMID 39409999, 2024). "We cannot state with certainty that the P/LP BRCA2, CHEK2, HOXB13, and MITF variants contributed to the patient's cancer, these might also be secondary findings." (PMID 38415346, 2024). "The results suggest that BOADICEA may be used to aid personalised cancer risk management and decision-making for BRCA1 and BRCA2 PV carriers." (PMID 38834293, 2024).
cancer (continued). "However, cancer cells, particularly those with mutations in certain DNA repair genes, such as BRCA1 or BRCA2, are more dependent on PARP (synthetic lethality)." (PMID 37296748, 2023). "In particular, the number of cancers with a Gleason score of seven or higher tends to be higher in cases with BRCA2 pathogenic variants than in those without variants." (PMID 37174127, 2023). "In particular, two major homologous recombination repair (HRR) genes, BRCA1 and BRCA2, become nonfunctional in cancer through loss of function (LOF) mutations or hypermutations in the promoter region." (PMID 37298484, 2023). "There is no clear evidence explaining the predisposition to cancer in male BRCA2 mutations carriers compared to BRCA1 mutation carriers." (PMID 38203374, 2023). "Furthermore, as DNA2 plays a role in DSB repair via HR pathways, the combination of d16 and PARPis can be utilized as a synthetic lethal therapy in BRCA1- and or BRCA2-proficient cancer cells and xenografts." (PMID 37756561, 2023). "Such tumor regression profile also indicated BRCA2 delivery and expression in the tumor tissue which might suppress the growth of 4T1 cancer cells in mice." (PMID 36631481, 2023). "The risk of PC is up to five-fold higher in BRCA2 variant carriers than in general population and has been reported to be more aggressive (frequently with Gleason scores ≥ 8) and associated with worse survival compared to BRCA wild-type cancers." (PMID 37347260, 2023). "In patient n.10, Myriad did not report as pathogenic the variant BRCA2 c.4284dup, which was indeed carried not only by the proband but also by other family members suffering from hereditary cancers." (PMID 38069422, 2023). "According to the proteomics, although the expression of TOP2A was also reduced for this comparison, there were multiple other changes in the DNA damage recognition/repair machinery that affected the overall outcome (e.g., reduction in breast cancer gene 2, BRCA2 and gain in PARP1)." (PMID 37242727, 2023). "Deletion of BRCA1 or BRCA2 induces the upregulation of TERRA RNA in cancer cells." (PMID 37108225, 2023). "For patients with information allowing definition of intrinsic-like subtypes, Luminal A-like cancer was associated with an increased risk of death among BRCA2 carriers and young non-carriers, contrasting with the lower risk among the older group." (PMID 38036573, 2023). "However, in the context of a second also seemingly benign Brca2 mutation, the added Rad51c NTDI mutation strongly drives cancer in these mice and confers cancer therapy sensitivity." (PMID 37488098, 2023). "From our NOP data, it is still controversial whether BRCA1, BRCA2, and MMR genes are associated with an increased risk of cancer in children and adolescents, and further studies are needed." (PMID 37916805, 2023). "PARPis were shown to be lethal in homologous recombination (HR)-deficient BRCA1/BRCA2-mutated cancers, likely because collapsed replication forks are no longer repaired." (PMID 36831435, 2023). "Importantly, NVB selectively kills cancer cells harboring HR deficiency (BRCA1- and BRCA2-deficiency) and potentiates the cytotoxic effect of PARP inhibition in HR-deficient cancer cells." (PMID 37510250, 2023). "However, both TSPAN8 and THRSP expression were lower in BRCA2-mutant and non-BRCA2-related cancers when compared to normal tissue." (PMID 37626143, 2023).